MEN1 (menin 1)
Diseases named in the same sentence as MEN1 in open-access papers (continued):
Sharing a sentence is not in itself a finding about the gene and the disease.
melanoma (continued). "Methylation of MEN1 is regulated by KRAS in lung adenocarcinoma, so it is possible that NRAS, the second most commonly mutated driver gene in melanoma, may similarly be responsible for the increased MEN1 promoter methylation observed in melanoma." (PMID 39336822, 2024). "Thus, we investigated whether MEN1 could relay some of the TGFβ tumor-suppressive response in melanoma." (PMID 38891107, 2024). "We found that the multiple endocrine neoplasia type 1 (MEN1) gene product Menin is required for the transforming growth factor beta (TGFβ) signaling pathway to induce cell growth arrest and apoptosis in vitro and prevent tumorigenesis in vivo in preclinical xenograft models of melanoma." (PMID 38891107, 2024). "Three MEN1 mutation-positive and one MEN1 mutation-negative patients had melanomas." (PMID 37484956, 2023). "Loss of heterozygosity was not screened for in the melanomas associated with MEN1." (PMID 36428828, 2022). "Moreover, MEN1 expression was reduced in nine out of eleven melanoma samples that were analyzed." (PMID 36428828, 2022). "The MEN1 gene has not been definitively implicated in melanoma pathogenesis." (PMID 36325452, 2022). "We excluded the following genes that were methylated and deleted in melanoma: PTEN, BRIMS1, FERMT3 (KIND3), AKAP12 (SSeCKS), CDKN2A, APAF-1, MTAP and MEN1." (PMID 34639015, 2021). "Only WT MEN1 could induce TGFβ-mediated luciferase activity in control WM278 MEN1 KD and WM793B MEN1 KD melanoma cells, consistent with the results observed with the proteasome inhibitor." (PMID 38891107, 2024). "The present study expands on these findings, highlighting MEN1 as a potent tumor suppressor downstream of TGFβ in nonendocrine tumors, such as melanoma." (PMID 38891107, 2024). "Melanomas were reported in other MEN1 cohorts, but a clear relationship between these lesions and MEN1 gene alteration has not been proved." (PMID 37484956, 2023). "As far as we currently know, the presence of a melanoma in a MEN1 patient is not part of the typical picture and it is probable that other genetic constellations or implications are responsible for this association." (PMID 36428828, 2022). "Melanoma has been reported as a cause of death in some studies whereas other publications studying mortality in MEN1 are notable for no deaths from melanoma." (PMID 36325452, 2022). "However, the melanoma–MEN1 correlation due to common genetic background is debatable; also, a higher prevalence of this most aggressive skin cancer in MEN1 when compared to the general population has not been proved." (PMID 36428828, 2022).
osteoporosis (8 papers, 2018 to 2025). A condition of reduced bone mass, with decreased cortical thickness and a decrease in the number and size of the trabeculae of cancellous bone (but normal chemical composition), resulting in increased fracture incidence. "From a clinical point of view, the screening of bone metabolism and osteoporosis risk should be routinely included in the diagnostic plan of MEN1 patients with PHPT, together with analysis for oncological monitoring." (PMID 34440663, 2021). "MEN1 patients have a higher risk of early onset osteoporosis, with respect to the general population of the same age, attributed to primary hyperparathyroidism (PHPT) and other endocrine dysfunctions typical of the syndrome." (PMID 34440460, 2021). "MEN1 patients are prone for severe morbidity such as osteoporosis caused by Phpt." (PMID 30254610, 2018). "Studies in patients with MEN1 have already shown that women aged between 20 and 35 years have a higher incidence of osteopenia and osteoporosis when compared to the general population of the same age group." (PMID 36967793, 2023). "MEN1 PHPT patients with osteopenia presented a significantly lower mean age of onset than those with osteoporosis (t-test p-value = 0.00013)." (PMID 34440663, 2021). "MEN1 PHPT patients with a normal BMD showed a significantly lower mean age compared to both MEN1 patients with osteoporosis (t-test p-value = 0.00006) and MEN1 patients with osteopenia (t-test p value = 0.039)." (PMID 34440663, 2021). "Persistent excess of PTH is responsible for increased bone resorption and reduction of calcium deposition on bone tissue, leading to a pathological loss of cortical and trabecular bone and early osteopenia/osteoporosis with risk of fragility fractures both in sporadic PHPT and MEN1-related PHPT." (PMID 30364322, 2018). "MEN1-associated PHPT, which develops in young adults and also in children and adolescents, can also severely alter the establishment of bone mass peak and be responsible for a higher risk of severe osteoporosis and fragility fractures." (PMID 30364322, 2018). "On the practical side, we should mention the need of using more scales to assess and follow the quality of life in MEN1/MPHPT individuals, including those with osteoporosis and prevalent fragility fractures." (PMID 40364143, 2025). "For 13 additional MEN1 PHPT patients, indication of the presence of pre-operative osteopenia or osteoporosis and age at diagnosis were reported in their medical records, in absence of DXA numeric parameters." (PMID 34440663, 2021). "By the age of 20–35 years, MEN1 women with PHPT showed a higher incidence of osteopenia and osteoporosis compared to the general population of the same age, with a consequent increased risk of fragility fracture." (PMID 34440663, 2021).
endocrine neoplasia (7 papers, 2012 to 2025). "The leukemia-driving activity of MLL fusion proteins relies on their interaction with menin, a protein encoded by the multiple endocrine neoplasia (MEN1) gene." (PMID 31590682, 2019). "It was recently reported that HIV-1 Tat transactivation required menin, which is a 610-amino acid protein encoded by the multiple endocrine neoplasia type 1 (MEN1) gene." (PMID 28178646, 2017). "Further investigations analyzing the regulation of menin targets (HOX and DLK1-MEG3 genes) during the initiation and progression of tumors found in MEN1 or MEN1-like sporadic endocrine tumors will be instrumental in correlating these events as biomarkers and/or causes of endocrine neoplasia." (PMID 22666422, 2012). "All of the gonadotroph PitNET showed in both, the primary and the recurrent lesions, SNV in the AIP (Aryl hydrocarbon receptor interacting protein rs64108, c.C682A, p.Q228K) and MEN1 (Multiple endocrine neoplasia type 1 rs2959656, c.A1621G, p.T541A) genes." (PMID 39217365, 2024). "MEN1 has been conventionally characterized as a heritable endocrine neoplasia, which may be familial or arise de novo." (PMID 39946193, 2025).
gastric NET (7 papers, 2012 to 2021). "Loss of heterozygosity at the MEN-1 locus on chromosome 11q has been clearly established in these type 2 gastric neuroendocrine tumours in contrast to type 1 gastric neuroendocrine tumours that are related to hypergastrinaemia due to atrophic gastritis." (PMID 24213225, 2012). "OS was associated with initial FSG levels ≥20x ULN, a pNET ≥2.0 cm on conventional imaging, synchronous liver metastases, multiple concurrent NETs, and gastroduodenoscopy suspicious for gastric NET in patients with MEN1." (PMID 31401809, 2019). "Gastric NET tumours are rare; but multiple, small gastric carcinoids (Type 2) may be found in over 70% of patients with MEN1 but account for only 5% of all gastric NETs." (PMID 28965289, 2017). "The influence of genetic background on tumour phenotype may therefore explain the differences observed in four previously reported Men1+/- conventional mouse models; for example, gastric neuroendocrine tumours were reported only in a mixed NIH Black Swiss and 129/SvEvTacFBR model." (PMID 32348957, 2020).
Hyperparathyroidism-jaw tumor syndrome (7 papers, 2017 to 2025). "First, we examined the ExAC cohort for variants previously reported as disease-causing in six genes associated with penetrant monogenic disorders (i.e., FHH, MEN1 and MEN2, hyperparathyroidism-jaw tumor syndrome, NF1, and VHL)." (PMID 29308445, 2017). "Familial PHPT consists of multiple endocrine neoplasia (MEN) type 1 (MEN1), type 2A (MEN2A), type 4 (MEN4) and hyperparathyroidism-jaw tumor syndrome (HPT-JT), caused by known germline genetic mutations." (PMID 36777354, 2023). "Genetic syndromes that promote the development of PHPT have an autosomal dominant inheritance pattern and include MEN1, MEN2, MEN4, and hyperparathyroidism-jaw tumor syndrome." (PMID 40277809, 2025). "In the younger population, other causes (mostly genetic) are involved, such as multiple endocrine neoplasms type 1, 2 and 4 (MEN1, MEN2, MEN4), hyperparathyroidism-jaw tumor syndrome (HPT-JT)." (PMID 37568342, 2023).
medullary thyroid carcinoma (7 papers, 2017 to 2025). "Most commonly, the first manifestation of MEN2 is medullary thyroid carcinoma, which strongly correlates with the underlying RET pathogenic variant (which is not the case in MEN1 for MEN1)." (PMID 40364143, 2025).
pancreatic NEN (7 papers, 2020 to 2025). "Preclinical studies as well as first observational studies in patients with MEN1 suggest that somatostatin analogues (SSA) might be effective for primary and secondary prevention of MEN1-associated pancreatic NEN." (PMID 40277511, 2025). "Our observations are comparable to those in tumors of the endocrine pancreas where LOH was shown for tumors but not for islet hyperplasia in MEN1." (PMID 38244045, 2024).
skin tumor (7 papers, 2021 to 2025). "MEN1 patients can develop malignancies other than classical endocrine tumors, including skin tumors." (PMID 38891107, 2024). "However, there are some case reports that present this type of skin cancer in MEN1." (PMID 36428828, 2022).
somatostatinoma (7 papers, 2012 to 2025). A rare, usually malignant neuroendocrine tumor arizing from delta cells. "These tumoral entities usually localize in the pancreas in MEN1, even though VIPoma has been described in the duodenum, and somatostatinoma both in the duodenum and the jejunum." (PMID 24213321, 2012). "Since clinically evident glucagonomas, VIPomas, somatostatinomas, and GHRHoma are rare in patients with MEN1, there is no consensus statement about their management and treatment." (PMID 24213321, 2012).
acute myeloid leukemia (6 papers, 2024 to 2025). Acute myeloid leukemia (AML) is a group of neoplasms arising from precursor cells committed to the myeloid cell-line differentiation. "The chemical structure of Menin-1 inhibitors (MI) has evolved, and more effective molecules are currently in clinical trials for the treatment of acute myeloid leukemia (AML)." (PMID 40722046, 2025). "They identified numerous targets, including Bromodomain-containing Protein 4 (BRD4), Histone Methyltransferase DOT1L (DOT1L), and Multiple endocrine neoplasia type 1 (MEN1) for Acute Myeloid Leukemia (AML)." (PMID 38725484, 2024). "Menin (MEN1) is a well-recognized powerful tumor promoter in acute leukemias (AL) with KMT2A rearrangements (KMT2Ar, also known as MLL) and mutant nucleophosmin 1 (NPM1m) acute myeloid leukemia (AML)." (PMID 39796769, 2025). "CRISPR/Cas9 screening platform have been used to identify genetic vulnerabilities in acute myeloid leukemia (AML) cells, including several established (such as DOT1L, BCL2, and MEN1) and novel (such as KAT2A) therapeutic targets for AML." (PMID 39696697, 2024).
adrenocortical tumors (6 papers, 2015 to 2025). "In our MEN1 patients with adrenocortical tumors, among the cascades with altered genes, one small pathway—with 18 nodes—was identified, i.e., WP3877—the MYD88 distinct input–output pathway." (PMID 38256138, 2024). "Asymptomatic adrenocortical tumors (ACTs) may be detected in 20–73% of patients with MEN1 depending on the imaging modality used for screening." (PMID 31263451, 2019). "Apart from MPHPT, MEN1 includes various endocrine tumours/NETs such as GEP-NETs, pituitary NETs (PitNETs), thymus and bronchial carcinoids, and adrenocortical tumours." (PMID 40364143, 2025). "Both non-functional and functional adrenocortical tumors occur in MEN1, and among these are included benign and malignant functional tumors causing CS." (PMID 37409236, 2023).
Alpha-thalassemia (6 papers, 2015 to 2025). Alpha-thalassemia is an inherited hemoglobinopathy characterized by impaired synthesis of alpha-globin chains leading to a variable clinical picture depending on the number of affected alleles. "Note that these TSC2 gene mutations have not been detected as frequently as multiple endocrine neoplasia type 1 (MEN1) and death domain-associated protein/alpha thalassemia/mental retardation syndrome X-linked (DAXX/ATRX) gene mutations." (PMID 25889454, 2015). "Two cases had a somatic MEN1 missense mutation and one case an ATRX (Alpha Thalassemia/intellectual disability syndrome X-linked) missense mutation." (PMID 37771441, 2023). "On the contrary, several gene mutations may characterize well-differentiated NETs, as observed with Menin 1 (MEN1), Death Domain Associated Protein (DAXX), and alpha-thalassemia/mental retardation, X-linked (ATRX) mutations in well-differentiated pancreatic NETs." (PMID 35186729, 2022).
breast tumors (6 papers, 2019 to 2025). "Recent studies suggested a possible increased risk of other malignancies, including thyroid and breast neoplasms, with current French MEN1 guidelines recommending breast screening for women with MEN1." (PMID 39826015, 2025). "MEN1 expression was found to be significantly increased in the breast tumor tissue with its predominant nuclear localization." (PMID 37437063, 2023). "Our analysis of mRNA expression using real-time PCR shows that MEN1 mRNA is upregulated in breast tumor samples as compared to the nearby normal tissue samples." (PMID 37437063, 2023). "Increased MEN1 expression was found in primary breast tumors relative to normal controls in The Cancer Genome Atlas (TCGA) cohort (p < 0.001)." (PMID 32971831, 2020). "In The Cancer Genome Atlas study of 510 breast tumors published in 2012, mutations in MEN1 were not reported." (PMID 36325452, 2022).
corticotropinomas (6 papers, 2019 to 2023). "Somatic mutations in the MEN1, PRKAR1A, and GNAS1 genes have also been reported in ACTHomas." (PMID 33266265, 2020).
Cowden syndrome (6 papers, 2007 to 2025). "Although mutations in these genes are typically associated with hereditary syndromes, neither patient displayed clinical features consistent with MEN1 or PTEN hamartoma tumor syndrome (Cowden syndrome)." (PMID 40762649, 2025).
Cushing syndrome (6 papers, 2019 to 2026). Cushing's syndrome (CS) encompasses a group of hormonal disorders caused by prolonged and high exposure levels to glucocorticoids that can be of either endogenous (adrenal cortex production) or exogenous (iatrogenic) origin. "Cushing syndrome (CS) within MEN1 presents complex diagnostic and therapeutic challenges." (PMID 41924515, 2026). "ACTH-independent Cushing’s syndrome due to adrenal neoplasia can represent the presenting manifestation of MEN1." (PMID 37409236, 2023). "Less than 10% of MEN1-associated ACTs demonstrate hormone hypersecretion, which can lead most commonly to primary hyperaldosteronism and/or ACTH-independent Cushing syndrome." (PMID 31263451, 2019). "Since both CD and ACTH-independent Cushing’s syndrome due to adrenal neoplasia can present in childhood or adolescence as its initial manifestation, MEN1 must be considered for all younger patients diagnosed with CS, especially in those with a potentially relevant family medical history." (PMID 37409236, 2023). "Notably, the index case manifested with an adrenocorticotropic hormone (ACTH)-producing pancreatic neuroendocrine carcinoma, leading to ectopic Cushing’s syndrome—a presentation not previously reported in MEN1." (PMID 39104820, 2024).
familial tumor syndrome (6 papers, 2020 to 2026). "PBMAH may also result from alterations in MC2R, PRKACA, and phosphodiesterase (PDE)11A genes, and it can occur as part of familial tumor syndromes such as McCune-Albright syndrome (GNAS), MEN1, familial APC, or hereditary leiomyomatosis and renal cell carcinoma (FH gene variant)." (PMID 41503047, 2026).
gastroenteropancreatic neuroendocrine tumors (6 papers, 2019 to 2025). "Loss of menin, either in the context of the MEN1 syndrome or resulting from sporadic mutations within the MEN1 locus, is associated with the development of gastroenteropancreatic neuroendocrine tumors (GEP-NETs)." (PMID 35330921, 2022). "Gastrointestinal neuroendocrine tumors appear to be less prevalent in MEN4 than in MEN1." (PMID 30990521, 2019).
hepatocellular carcinoma (6 papers, 2015 to 2025). A malignant tumor that arises from hepatocytes. "Differential expression profile analysis revealed that Men1 expression was significantly upregulated in hepatocellular carcinoma (HCC) and was at a central node." (PMID 40651612, 2025). "Patients with overexpression of MEN1 in prostate and hepatocellular carcinoma reportedly show poor survival when compared to patients with low MEN1 expression." (PMID 37437063, 2023). "Second, MEN1 and NFκB/p65 were co-expressed in hepatocellular carcinoma (HCC) tissues, adjacent normal liver tissues and various cell lines (including THLE-3, HepG2, Hep3B, HuH-7 and Li-7 cells)." (PMID 26157642, 2015). "Indeed, in the hepatocellular carcinoma cell line HepG2, MEN1-KD did not inhibit the transcription of lysosomal and autophagic genes such as CTSB and SQSTM1." (PMID 40057469, 2025).
lymph node metastasis (6 papers, 2019 to 2025). "Among the 17 patients with germline mutations, only one had a recurrence (lymph node metastasis in a patient with MEN1)." (PMID 38201527, 2023).
McCune-Albright syndrome (6 papers, 2011 to 2026). McCune-Albright syndrome (MAS) is classically defined by the clinical triad of fibrous dysplasia of bone (FD), cafe-au-lait skin spots, and precocious puberty (PP). "Four patients had an identified genetic mutation (McCune-Albright syndrome: n = 1; MEN1: n = 1; AIP: n = 2); the remaining three cases were sporadic." (PMID 22024364, 2011). "These defects include multiple neoplasia syndromes, including the multiple endocrine neoplasia type 1 (MEN1), the Carney complex and McCune-Albright syndrome." (PMID 22024364, 2011). "In addition to postzygotic somatic mosaicism of GNAS in McCune-Albright syndrome, rare examples of hereditary PBMAH have been described in the setting of APC-, MEN1-, FH-, PDE8B-, and PDE11A variant-driven pathogenesis." (PMID 29594118, 2018).
multiple endocrine neoplasia type 4 (6 papers, 2021 to 2025). Multiple endocrine neoplasia type 4 (MEN4) is a very rare form of MEN, an inherited cancer syndrome, characterized by parathyroid and anterior pituitary tumors, possibly associated with adrenal, renal, and reproductive organ tumors. "Inactivating mutations of the CDNK1B tumor suppressor gene are responsible for the development of multiple endocrine neoplasia type 4 (MEN4), a clinical phenocopy of MEN1." (PMID 34298972, 2021).